ALB (albumin)
Diseases named in the same sentence as ALB in open-access papers (continued):
Sharing a sentence is not in itself a finding about the gene and the disease.
dermatitis (4 papers, 2013 to 2026). An inflammatory process affecting the skin. "Univariate analysis identified three significant risk factors: DM (p = 0.024), serum albumin ≤ 3.5 g/dL (p = 0.042), and oblateness of the stoma (p = 0.039), all of which were associated with worsening peristomal skin disorders." (PMID 41298770, 2025). "The reported decrease in serum albumin in the positive control group could be explained by the loss of plasma proteins from the exudative dermatitis and the persistent sucking of fluid by the mites, impaired liver function, and oxidative stress." (PMID 37964301, 2023). "We speculate that the albumin component of nab-paclitaxel might be the cause of the skin disorder." (PMID 23659317, 2013). "The albumin component of nab-paclitaxel might be the cause of the skin disorder." (PMID 23659317, 2013).
diabetic macular edema (4 papers, 2015 to 2025). "Although we only analyzed serum Cre, eGFR as markers of renal function, additional indicators—such as urinary protein and the urinary albumin-to-creatinine ratio (ACR)—are also associated with the risk of developing diabetic macular edema (DME)." (PMID 40019637, 2025).
endocarditis (4 papers, 2022 to 2024). Inflammation of the endocardium. "In particular, a dose increase may be necessary in patients with enhanced renal function and high serum albumin levels, or in patients with endocarditis and severe infection." (PMID 36506535, 2022). "In addition, with the same eGFR and serum albumin concentrations, patients with endocarditis and severe infection require a higher loading dose to achieve PTA ≥ 80%." (PMID 36506535, 2022). "Some of these diseases can also increase CRP and reduce albumin, so it can be difficult to distinguish whether abnormal GPS is due to endocarditis or its complications." (PMID 39292095, 2024).
falciparum malaria (4 papers, 2010 to 2021). "Yet, with acute falciparum malaria, serum concentrations of AAG in non-immune human patients increase two-fold within 24 hours whereas plasma levels of albumin decrease by 30%." (PMID 32756590, 2020).
fasciolosis (4 papers, 2021 to 2024). "Conversely, E%, E#, RBC, HGB, and ALB levels were significantly higher in patients with human fascioliasis than in those with bacterial liver abscess." (PMID 39686435, 2024). "Investigations into the digestion of protein substrates from mammalian hosts susceptible to Fasciola infection have shown that NEJ proteinases catalyse the hydrolysis of gelatin, collagen, fibronectin, serum albumin, immunoglobulins and haemoglobin." (PMID 34944270, 2021). "Low ALB and high immunoglobulin are commonly seen in fasciolosis." (PMID 35071045, 2021). "Patients in the human fascioliasis group demonstrated significantly lower WBC, N%, TBI, ALT, AST, ALP, GGT, and FIB levels and higher E%, E#, RBC, TP, ALB, CA-125, CA-199, and CA-724 levels than patients in the bacterial liver abscess group." (PMID 39686435, 2024). "Our results indicate that reduced blood albumin levels during fasciolosis may not exclusively be due to liver tissue damage or blood loss, and that other mechanisms involving the hepatic lymph node and other tissues can also contribute to reduce overall albumin levels." (PMID 34122452, 2021).
fetal growth restriction (4 papers, 2021 to 2024). A fetus that does not grow beyond the 10th percentile of conventionally accepted weight for gestational age. "In the same line of thought, a recent study demonstrated a reverse U-shaped association between maternal serum albumin and fetal growth, with high levels of maternal serum albumin contributing to the development of fetal growth restriction." (PMID 36474218, 2022). "It was demonstrated that decline in serum albumin levels could predict the development of preeclampsia, while another study showed an association between hyperalbuminemia and development of fetal growth restriction." (PMID 36474218, 2022). "A rat model simulating fetal growth restriction, induced by protein-energy restriction, was used to elucidate the relationship between maternal nutritional status, maternal serum ALB redox state, and birth weight of the offspring." (PMID 34067270, 2021).
food allergy (4 papers, 2013 to 2023). Gastrointestinal disturbances, skin eruptions, or shock due to allergic reactions to allergens in food. "We therefore calculated the OR for clinical relevant food allergy when sensitized to 7S/11S globulin or 2S albumin fractions." (PMID 37007648, 2023). "N-glycosylation is also involved in food allergy, as several identified, N-glycosylated albumin proteins in wheat shared high sequence similarities with known food allergens." (PMID 28328971, 2017). "This study has shown that the disruption of the protein structure of Brazil nut 2S albumin decreased the sensitizing potential in a Brown Norway rat food allergy model, whereas the immunogenicity of 2S albumin remained preserved." (PMID 24180644, 2013). "Thus, our aim was to evaluate the effect of the extrusion process on the sensitizing and allergenic potential of the albumin and globulin fractions from amaranth in a BALB/c mouse model of food allergy." (PMID 30897829, 2019).
gastric outlet obstruction (4 papers, 2019 to 2024). The hindering of output from the STOMACH into the SMALL INTESTINE. "There were significantly lower levels of pre-operative serum albumin in patients presenting with gastric outlet obstruction compared to those without 34.0 (IQR 34.0–42.0) vs 38.0 (IGR 27.5–37.8) g/L, respectively, p = 0.014." (PMID 30972486, 2019).
growth failure (4 papers, 2014 to 2025). "There was a significant correlation between growth failure and serum albumin levels below 3.5 g/dL (p=0.002)." (PMID 27086477, 2016). "It includes growth failure and serum albumin level that are not usually associated with ALF." (PMID 35054127, 2022). "The PELD score, calculated from the patients' albumin, bilirubin and INR, together with the age and degree of growth failure, has been developed to predict outcomes in children with chronic liver disease." (PMID 40433928, 2025).
hemangioma (4 papers, 2013 to 2022). A benign vascular lesion characterized by the formation of capillary-sized or cavernous vascular channels. "In HOXB7-Cre driven Vhlh knockout mice, hemangiomas develop with higher penetrance (90 % vs ~40 %) and at a younger age (4–6 weeks versus ~3–8 months) compared to the Albumin-Cre Vhlh knockout mice." (PMID 27733136, 2016). "The more hepatocyte-specific Cre (Albumin-Cre) driven Vhlh knockout also generated hemangiomas, albeit more at the microscopic level." (PMID 27733136, 2016). "However, despite superficial similarity of the phenotypes, several findings indicate that the mechanism of hemangioma formation is different in hepatocyte-specific Albumin-Cre driven and HOXB7-Cre driven Vhlh knockout mice." (PMID 27733136, 2016). "Hif-2α was found to mediate up-regulation of erythropoietin and multiple pro-angiogenic cytokines in these mouse models, and inactivation of Hif-2α or Hif-1β/Arnt, but not Hif-1α, rescued hemangiomas in PEPCK-Cre or Albumin-Cre driven Vhlh knockout mice." (PMID 27733136, 2016). "Furthermore, the hemangiomas in HOXB7-Cre driven Vhlh knockouts exhibit extramedullary hematopoiesis that is also observed in human hemangioblastoma but not in liver with hepatocyte Vhlh knockout (either Albumin-Cre or PEPCK-Cre driven)." (PMID 27733136, 2016).
Hernia (4 papers, 2023 to 2025). "Prognostic indicators containing objective measures of inflammatory and immune responses, that is, lymphopenia and significantly raised CRP and declined albumin, could foresee strangulation and requirement of resection in the patient with incarcerated abdominal hernias." (PMID 40389774, 2025). "Hernia surgery was shown to increase CRP, IL-6 levels, leukocyte count, neutrophil count, IL-1 levels, IL-10 levels, fibrinogen, and α1-antitrypsin, and decrease lymphocyte counts and albumin during the first 24 postoperative hours." (PMID 36739352, 2023). "By evaluating CRP as an inflammation marker and albumin as a negative acute-phase protein, we hypothesized that PNI will be a major factor in the prognosis of strangulation and resection in abdominal hernia patients with incarceration." (PMID 40389774, 2025).
HIV-associated nephropathy (4 papers, 2016 to 2022). Renal disease in human immunodeficiency virus (HIV)-infected patients. "The secondary outcomes included renal impairment (eGFR <60 ml/min per 1.73 m2), albuminuria (albumin-to-creatinine ratio [ACR] >30 mg/mmol), and biopsy-proven HIV-associated nephropathy (HIVAN)." (PMID 35497797, 2022). "We were not able to measure urine albumin-creatinine ratio to explain the significance of the proteinuria and how it relates to HIV-associated nephropathy (HIVAN)." (PMID 29606987, 2018).
Huntington disease (4 papers, 2011 to 2026). Huntington disease (HD) is a rare neurodegenerative disorder of the central nervous system characterized by unwanted choreatic movements, behavioral and psychiatric disturbances and dementia. "In an R6/2 mouse model of Huntington’s disease, albumin-fluorescein isothiocyanate conjugate (FITC-albumin) was found in the brain at early and late disease stages, confirming BBB breakdown under these conditions." (PMID 35631573, 2022).
hyperlipemia (4 papers, 2020 to 2025). "The serum level of Se was positively associated with TGs (r = 0.85, p = 0.005) and ALB (r = 0.73, p = 0.014) in the hyperlipemia group." (PMID 39729004, 2024). "The AUCs of serum TP and ALB levels in the hyperlipemia and healthy groups were 0.510 and 0.889, with the optimum cutoff points being 84.78 g/L and 29.77 g/L, respectively." (PMID 39729004, 2024). "The serum level of selenium was significantly lower (p < 0.05) and positively correlated with TGs (r = 0.85) and ALB (r = 0.73) in the hyperlipemia group." (PMID 39729004, 2024). "The multivariate analysis displayed that sC5b-9, CH50, smoking, hyperlipemia, albumin level, serum CEA level, KPS score, surgery, and application of platinum were independent risk factors." (PMID 33193878, 2020). "Meanwhile, smoking, hyperlipemia, albumin level, serum CEA level, KPS score, surgery, and application of platinum were also the independent risk factors for OS of NSCLC patients." (PMID 33193878, 2020).
Hypocholesterolemia (4 papers, 2016 to 2025). An decreased concentration of cholesterol in the blood. "Additionally, they observed a close correlation between elevated CRP levels, reduced serum albumin levels, and hypocholesterolemia." (PMID 40339352, 2025).
Hypofibrinogenemia (4 papers, 2021 to 2022). Decreased concentration of fibrinogen in the blood. "In both diseases, the albumin and LDH levels were significantly higher and the CRP levels were significantly lower in patients with hypofibrinogenemia than in those without hypofibrinogenemia." (PMID 33632246, 2021). "Furthermore plasma exchange (PLEX), preferably against plasma rather than albumin, could represent an alternative option for reducing the amount of circulating PF4/vaccine complexes and correcting hypofibrinogenemia." (PMID 35821156, 2022).
hypopharyngeal cancer (4 papers, 2020 to 2025). Carcinoma, predominantly squamous cell, arising from the epithelial cells of the hypopharynx. "A reported clinical prediction model for survival in hypopharynx cancer consisted of gender, subsite, TNM classification, Adult Comorbidity Evaluation-27 score (ACE27), body mass index (BMI), hemoglobin, albumin, and leukocyte count." (PMID 37025592, 2023).
hypovitaminosis D (4 papers, 2020 to 2024). "Particular attention should be paid to the problem of hypovitaminosis D in dark-skinned children who live in northern latitudes, with a severe course of the disease and early onset, low albumin level, lower BMI, and abnormalities observed in the densitometry examination." (PMID 39064704, 2024). "DBP knock-out mice, in which vitD metabolites are presumably all free and albumin-bound, do not show evidence of vitD deficiency and do not develop rickets." (PMID 32041235, 2020). "The measurement of plasma calcium (preferably ionized if feasible, or alternatively albumin-corrected), phosphate, ALP, creatinine, PTH and 25(OH)D are part of the standard work-up for any form of rickets or osteomalacia." (PMID 33815294, 2021).
infective endocarditis (4 papers, 2023 to 2026). Infective endocarditis (IE) is an infection of the inner lining of the heart chambers (endocardium) and valves. "Analysis revealed that infective endocarditis (IE), platelet count, and serum fibrinogen and albumin levels were associated with HR." (PMID 39303137, 2024). "Glasgow prognosis score, determined using albumin and C-reactive protein levels, is a simple and practical index for predicting the prognosis of patients hospitalized with infective endocarditis." (PMID 38656008, 2024).
Invasive ductal carcinoma (4 papers, 2020 to 2025). "C-reactive protein to albumin ratio is a significant predictor for survival in ductal adenocarcinoma, yet its clinical relevance should be explored in conjunction with the pathology parameters and adjuvant therapy." (PMID 37322265, 2023). "In the context of breast invasive ductal carcinoma, this research aims to retrospectively evaluate by preoperative plasma albumin to fibrinogen ratio (AFR) and forecast oncological outcome and recurrence." (PMID 32590741, 2020). "C-reactive protein to albumin ratio, but not Glasgow prognostic score and modified Glasgow prognostic score, was linked to survival following pancreatectomy for ductal adenocarcinoma." (PMID 37322265, 2023).
ischemic cardiomyopathy (4 papers, 2012 to 2026). Ischemic cardiomyopathy is a cardiomyopathy in which a weakness in the muscle of the heart due to inadequate oxygen delivery to the myocardium with coronary artery disease being the most common cause. "First experiments to analyse human proteome from patients with ischemic cardiomyopathies by DIGE 2-DE showed a high concentration of human serum albumin, which interfered with the adequate focusing and detection of lower abundance proteins." (PMID 22384053, 2012).
joint effusion (4 papers, 2020 to 2026). "In addition to measurements of joint swelling, we showed joint effusion by elevated levels of serum albumin and serum-derived bikunin-containing complexes in the synovial fluids." (PMID 41576101, 2026).
keratoconus (4 papers, 2022 to 2026). A degenerative, structural disorder of the eye, characterized by a cone-shaped protrusion of the cornea. "Albumin, however, showed decreased levels in the keratoconus group, consistent with previous studies." (PMID 41601845, 2026). "Namely, there is an apparent overlap of differentially expressed prolactin-induced protein (PIP), lipocalin-1, lysozyme C, zinc alpha 2-glycoprotein and serum albumin between keratoconus and ocular allergy sufferers." (PMID 35205178, 2022).
knee osteoarthritis (4 papers, 2016 to 2024). "In 2014, a multicenter, randomized, double-blind study assessed the efficacy and safety of the Low Molecular Weight Fraction of 5% human serum albumin (LMWF-5A) in 329 knee osteoarthritis patients." (PMID 39598266, 2024). "Low molecular weight fraction of 5% (LMWF-5A) human serum albumin is an intra-articular injection that emerged for the treatment of knee osteoarthritis." (PMID 37529519, 2023). "In this study, we constructed an albumin magnetic sphere with specific targeting of CD146 (CD146-AMs) for sorting a subpopulation of CD146-positive ADSCs (CD146 + ADSCs) and explored the role of CD146 + ADSCs on joint pain and cartilage repair in rats with knee osteoarthritis (KOA)." (PMID 38102700, 2023).
leishmaniasis (4 papers, 2017 to 2024). Infectious disease that is transmitted through the bite of hematophagous female phlebotomine sand flies. "Dogs with leishmaniasis showed a significantly lower red blood cell count, hemoglobin, hematocrit, and serum albumin concentration and significantly higher serum globulin concentrations than healthy dogs (control group)." (PMID 38241360, 2024). "Increased levels of serum proteins and globulins are commonly detected in dogs with leishmaniasis, while levels of albumin and the A/G ratio are frequently decreased." (PMID 34651045, 2021). "An increase in plasma proteins secondary to hyperglobulinemia and a decrease in plasma albumin, that result in a reduced A/G ratio, are common findings in dogs with leishmaniasis." (PMID 28982165, 2017).
liver toxicity (4 papers, 2015 to 2023). "ALT, AST, ALP, GGT, total bilirubin, and albumin are considered markers of liver toxicity." (PMID 35237941, 2023). "Abnormal metabolism, downregulation of TP, ALB and GLB and upregulation of metabolic enzyme activities (TBIL, ALP, ALT, and AST) in the plasma have been reported as indicators for liver toxicity." (PMID 34945637, 2021). "Also there are not similar studies about ALP, ALB, and TP levels in MTX induced liver toxicity." (PMID 26199067, 2015).
lower respiratory tract infection (4 papers, 2021 to 2024). "The value of the LDH to ALB ratio can be used as an independent prognostic factor for mortality in patients with lower respiratory tract infection." (PMID 37614558, 2023).
lung squamous cell carcinoma (4 papers, 2014 to 2025). "Abraxane has the active agent of paclitaxel, which is an approved agentfor treatment of squamous cell lung cancer, as well as the albumin-bound propertywhich increases the drug distribution and concentration to a new level." (PMID 25239521, 2014). "Non-albumin proteins (β=-0.272, P=0.020, FDR=0.180) and total protein (β=-0.402, P=0.009, FDR=0.072) were inversely related to lung squamous cell carcinoma." (PMID 39687887, 2024).
Lyme Neuroborreliosis (4 papers, 2011 to 2023). "Patients with definite Lyme neuroborreliosis had significantly more neurological symptoms outside the paretic area of the face and significantly higher levels of mononuclear cells and albumin in their cerebrospinal fluid." (PMID 21831262, 2011). "In contrast to other viral (e.g., TBE) or bacterial infections, CSF-CXCL13 levels in neuroborreliosis showed a significant decrease only a few days after the start of antibiotic therapy, in contrast to the leucocyte count, CSF/serum albumin ratio, or Bb-specific IgG AI." (PMID 38203597, 2023). "CSF-CXCL13 is the marker in neuroborreliosis that, unlike other viral and bacterial CNS infections, declines more sharply and rapidly than the leucocyte count, albumin quotient, and Bb-specific IgG AI." (PMID 38203597, 2023). "In addition, CSF-CXCL13 serves as a treatment response marker in neuroborreliosis that decreases most strongly and rapidly during therapy, independent of the decrease in the CSF/serum albumin ratio or total cell count." (PMID 38203597, 2023).
Lymphatic Metastasis (4 papers, 2016 to 2026). Transfer of a neoplasm from its primary site to lymph nodes or to distant parts of the body by way of the lymphatic system. "Univariate analysis identified several factors significantly associated with survival, including inflammatory markers, smoking, antibacterial use, lymphatic metastasis, radiotherapy, intraoperative blood loss, and preoperative albumin levels." (PMID 42100267, 2026). "In our study, we found that mid- and low-thoracic tumor, lymphatic metastasis especially abdominal and retroperitoneal lymph node invasion, distant metastasis and low albumin level were associated with poor prognosis in patients with inoperable ESCC." (PMID 28783764, 2017). "Univariate analysis revealed that lymphatic metastasis, PT, MVI, HBV, GAR, ALB, AST, Child-Pugh grade, neutrophils, CEA, AFP, and CA19-9 were significant risk factors." (PMID 41210683, 2025).
male infertility (4 papers, 2014 to 2023). The inability of the male to effect fertilization of an ovum after a specified period of unprotected intercourse. "ALB and FN1 have been suggested as potential biomarkers for oxidative stress in terms of male infertility factors." (PMID 37799407, 2023).